RN7SL585P (RNA, 7SL, cytoplasmic 585, pseudogene)
Gene: Miscellaneous RNA gene on chromosome 13 (94,699,223 to 94,699,502, reverse strand). Ensembl gene ENSG00000274168.
Homologues: Orthologues: chimpanzee Metazoa_SRP (99% identical). Paralogues in human: RN7SL1 (84% identical), RN7SL2 (84% identical), RN7SL45P (84% identical), RN7SL3 (82% identical), RN7SL566P (82% identical), RN7SL126P (81% identical), RN7SL296P (81% identical), RN7SL381P (81% identical), RN7SL383P (81% identical), RN7SL118P (81% identical), RN7SL246P (81% identical), RN7SL444P (81% identical), and 705 more.